FOXP3 (forkhead box P3)
Diseases named in the same sentence as FOXP3 in open-access papers (continued):
Sharing a sentence is not in itself a finding about the gene and the disease.
Autoimmunity (continued). "The protein synthesized by the FOXP3 gene is a key regulator of T cell activation, more specifically Treg (regulatory T cells) that prevent autoimmunity." (PMID 33791232, 2021). "We have shown earlier that pCons peptide delayed the onset of autoimmunity in lupus mouse model by inducing immune tolerance and up-regulating FoxP3 in T cells which are suppressive." (PMID 34093553, 2021). "The Treg cells express the FoxP3 transcription factor and are critical for the prevention of excess immunopathology or autoimmunity through multiple mechanisms." (PMID 31990927, 2020). "As the major regulator of T cell-mediated immunity, regulatory CD4+ T (Treg) cells express forkhead box P3 (FOXP3) transcription factor and suppress aberrant immune responses that result in autoimmune disorders." (PMID 32148437, 2020). "Regulatory T-cells (Tregs), a subset of CD4+ T-cells that express forkhead box protein P3 (FOXP3), play a major role in preventing autoimmunity by dampening immune responses." (PMID 33353234, 2020). "Foxp3+ regulatory T (Treg) cells are essential for maintaining peripheral tolerance and preventing autoimmunity." (PMID 32251280, 2020). "Tregs, the regulation of which is driven by the transcription factor Foxp3, are particularly important for limiting autoimmunity and chronic inflammation." (PMID 33391265, 2020). "Regulatory T cells (Tregs) are uniformly FoxP3+ and are essential for maintaining immune homeostasis, preventing autoimmunity, and regulating chronic inflammatory diseases." (PMID 32891157, 2020). "CD4+CD25+Foxp3+ regulatory T cells (Tregs) are central in controlling the magnitude of an immune response thereby regulating autoimmunity and maintaining mucosal tolerance." (PMID 33240286, 2020). "T follicular regulatory (Tfr) cells are a subset of FOXP3 Treg cells that also express PD-1, ICOS, CXCR5, CD25, Bcl-6, and Foxp3 and suppress Tfh–B cell interactions to limit autoimmunity." (PMID 32973682, 2020). "nTregs arise from CD4+ single positive thymocytes, leave the thymus as FOXP3+ nTregs, and are enriched for T cell receptors (TCRs) that have a high affinity for self-peptides, thus playing an important role in autoimmunity." (PMID 32977677, 2020). "The role of Foxp3 has been further corroborated in mice where the experimental depletion of Foxp3+ Tregs in healthy adult mice has been found to provoke autoimmunity and death." (PMID 32235291, 2020). "Given that Foxp3 is considered the master regulator of Tregs and its absence can result in severe autoimmunity, it is reasonable to assume that the long-term lineage stability of Tregs is highly dependent on the stability of Foxp3 expression." (PMID 33322482, 2020). "Although they are indispensable at preventing autoimmunity, Foxp3-expressing Tregs has been known to suppress effective anti-tumour immunity." (PMID 32645977, 2020). "Taken together, the analysis of FOXP3 isoforms can elucidate impaired tolerance induction and exaggerated T-cell responses in autoimmunity and chronic diseases." (PMID 33194927, 2020). "Animal models revealed that development of autoimmunity was due to defects in the CD4+CD25+FoxP3+ Treg cell population." (PMID 32256489, 2020). "Studies on autoimmune disorders have shown that ex-FoxP3+IL-17+ cells are accumulated selectively at the inflammation sites." (PMID 31024835, 2019). "For this reason, impaired Foxp3 expression leads to in vitro and in vivo defective suppressive function, resulting in T-cell mediated autoimmunity." (PMID 32117202, 2019). "Collectively, these observations suggest an important role of Foxp3 in autoimmunity, and strongly support a rationale for indirectly or directly targeting Foxp3 as a treatment stratagem for autoimmune diseases." (PMID 30974919, 2019). "PD-1 signaling is indeed required for the maintenance of functional CD4+CD25+FoxP3+ Tregs to control autoimmunity." (PMID 30650147, 2019).
Autoimmunity (continued). "Mutation of the FOXP3 gene in humans leads to immunodysregulation polyendocrinopathy enteropathy X-linked (IPEX) syndrome causing dysfunctional Tregs, severe autoimmunity, and premature death." (PMID 31142749, 2019). "Our data is consistent with the results of the previous study where depletion of Foxp3+ cells in adult mice using DT injections led to accelerated onset of multiorgan, lethal autoimmunity and lymphoproliferation." (PMID 31653839, 2019). "In the breach of immunological tolerance and in autoimmunity, changes in the microenvironmental cues perturb the transcriptional and epigenetic regulation of Foxp3, resulting into an impaired Treg cell generation and suppressive function." (PMID 32117202, 2019). "Meanwhile, downregulation of EOS impaired and reduced Foxp3-mediated gene repression, thereby leading to Treg dysfunction and autoimmunity." (PMID 31856855, 2019). "In this review, we summarize the molecular mechanisms controlling the epigenetic, transcriptional, translational, and post-translational regulation of Foxp3 in health and autoimmunity." (PMID 32117202, 2019). "From an immunopathological perspective, the analysis of murine and human T cell samples with recent onset of autoimmunity/T1D directly links Tet2 abundance and the methylation status of the Foxp3 CNS2 with islet autoimmunity in vivo." (PMID 31836704, 2019). "Foxp3+ regulatory T cells (Tregs) are indispensable for the maintenance of tolerance to self and prevention of autoimmunity." (PMID 31776355, 2019). "CD4+FOXP3+ regulatory T cells (Tregs) are a specialized subset of helper T cells that have a crucial role in preventing autoimmunity in murine models, including the NOD mouse model for T1D." (PMID 30723474, 2019). "O-GlcNAc-deficient Treg cells develop normally but display modestly reduced FOXP3 expression, strongly impaired lineage stability and effector function, and ultimately fatal autoimmunity in mice." (PMID 30664665, 2019). "The role of FOXP3+ Tregs is critical for controlling organ-specific autoimmunity, as demonstrated by the early onset of autoimmune enteropathy and endocrinopathy in IPEX patients and in mice harboring FOXP3 mutations." (PMID 29686686, 2018). "CD4+ regulatory T cells express the transcription factor FoxP3 and are critical in the prevention of excess immunopathology or autoimmunity through multiple mechanisms." (PMID 30429675, 2018). "When γδ T cells are activated and their adenosine-binding activity is greatly increased there is a net-decrease in extracellular adenosine resulting in inhibition of Foxp3+ T cells and enhancement of autoimmunity." (PMID 29771938, 2018). "Foxp3+CD4+ regulatory T (Treg) cells are essential for preventing fatal autoimmunity and safeguard immune homeostasis in vivo." (PMID 30560927, 2018). "We screened all participants for the seven genes known to cause monogenic autoimmunity that can include diabetes (AIRE, IL2RA, FOXP3, LRBA, STAT1, STAT3, STAT5B)." (PMID 29417186, 2018). "In this work, we focus in the population of CD4+CD25+ T cells and CD4+CD25+FOXP3+ T cells (considered to be part of Treg cells classification), given that these cells play key roles in self-tolerance and autoimmunity." (PMID 29928277, 2018). "Although CD4+Foxp3+ regulatory T cells (Treg) are crucial for prevention of autoimmunity, the therapeutic effect of these cells on lupus nephritis is not satisfactory." (PMID 29441062, 2018). "Flicr is selectively expressed in both human and mouse T regulatory cells and negatively regulates FOXP3 in cis leading to decreased Treg function and heightened autoimmunity." (PMID 30619315, 2018). "Tregs, characterized by expressing CD4, CD25, and Forkhead box P3 (Foxp3) transcription factor, play pivotal roles in protecting an individual from autoimmunity." (PMID 30459760, 2018). "CD4+CD25+FoxP3+ Tregs are highly involved in the regulation of immune responses and preventing autoimmunity." (PMID 30093899, 2018).
Autoimmunity (continued). "It is well established that thymic selection of a repertoire of self-reactive Foxp3+ T-cells provides an essential mechanism to minimize reactions to self-antigens in the periphery, and thus aid in the prevention of autoimmunity." (PMID 30333832, 2018). "Another study demonstrated that FOXP3+ regulatory T cell development and function require histone/protein deacetylase 3, and HDAC3-deficient mice died from autoimmunity by 4–6 weeks of age." (PMID 30402512, 2018). "Humans that lack a functional Treg cell population, characterized by their expression of the Foxp3, develop a lethal autoimmune disorder, which can be recapitulated in mice via Foxp3 deletion." (PMID 29482595, 2018). "The genome organizer SATB1, which is highly expressed during most stages of T cell thymic selection, was recently involved in setting-up thymic-derived Treg cell functional features and ability to prevent autoimmunity before Foxp3 is turned on27." (PMID 30560927, 2018). "By contrast, regulatory CD4+ T cells (Treg), characterized by expression of the transcription factor forkhead box P3 (FOXP3), have a key role in limiting inflammation and preventing autoimmunity by suppressing the activity of other immune cell types." (PMID 30320109, 2018). "Nevertheless, ALPS patients do not present with clinical features observed in “Tregopathies” (i.e., FOXP3 or CTLA-4 deficiencies) such as lymphocytic tissue infiltrations and organ-specific autoimmunity, in particular autoimmune enteropathy." (PMID 29686686, 2018). "Stable growth of autoreactive, TGF-β-induced FOXP3+ Tregs represents a critical prerequisite for effective Treg adoptive immunotherapies of autoimmunity and chronic inflammatory disease." (PMID 29312311, 2017). "A Treg-specific deletion of the E3 ubiquitin ligase, Itch, resulted in a widespread autoimmune disorder that was shown to be due to acquisition of Th2-cytokine production by Foxp3+ Tregs44." (PMID 29213081, 2017). "CD4+ CD25+ FOXP3+ regulatory T cells (Tregs) mediate an integral role in controlling autoimmunity and chronic inflammatory disorders." (PMID 29312311, 2017). "Conversely, therapies that increase the number or functional capacity of FOXP3+ Tregs can lead to prevention or cure of disease in preclinical models of autoimmunity, including type 1 diabetes." (PMID 28770318, 2017). "On the other hand, the CD4+ CD25+ Foxp3+ Treg cells, as protective factors in the autoimmunity and tissue damaging process, are also targets for various therapeutic treatments." (PMID 28198408, 2017). "While rebound Tregs are dysfunctional 32, DT‐resistant Foxp3+ Tregs have been shown to protect against lethal autoimmunity and suffice to control the self‐reactive (SR) CD4+ T cells during chronic mouse hepatitis virus infection." (PMID 28621034, 2017). "Foxp3+ T-regulatory (Treg) cells play important roles in maintaining the immune system by moderating the intensity of immune responses and preventing autoimmunity." (PMID 29236775, 2017). "This perception is in accordance with our vision that milk exosomal miRNAs shape the epigenetic environment of FoxP3-driven tolerance induction, a key mechanism for the prevention of autoimmunity and allergy." (PMID 28933365, 2017). "IL-17 also inhibits FOXP3 expression and has an important role in the progress of autoimmune disorders." (PMID 28824424, 2017). "FOXP3+ regulatory T cell (Treg) based cellular therapies represent promising therapeutic options in autoimmunity, allergy, transplantation and prevention of Graft Versus Host (GVH) Disease." (PMID 29285209, 2017). "As one important subtype of T cells, CD4+CD25+ forkhead box p3+ (Foxp3+) Treg cells inhibit autoimmunity and protect the tissue against injury and their development is controlled by Foxp3." (PMID 28690663, 2017). "Increased induction of Smad3 by Ash1l subsequently facilitates Foxp3 expression, contributing to the polarization of Treg cells and prevention of autoimmunity." (PMID 28598443, 2017).
Autoimmunity (continued). "IL-35 is produced by forkhead box P3+ Treg cells and activated B cells and has important roles in preventing autoimmunity, maintaining self-tolerance, and suppressing antitumor immune responses." (PMID 29123149, 2017). "Antigen-specific IL-10-secreting CD4+ T cells (Tr1) and Foxp3+ regulatory T cells (Tregs), both known to control autoimmunity and induced following JHMV infection, were assessed for their relative in vivo suppressive function of SR T cells." (PMID 27708643, 2016). "A primary role of Foxp3+ Tregs within draining lymph nodes was also observed in other infectious models, as well as during cancer and autoimmunity." (PMID 27708643, 2016). "Tregs (FOXP3+) play an important role in the control of autoimmunity, maintenance of transplantation tolerance and suppression of anticancer immune responses." (PMID 27777963, 2016). "Here, we provide novel conceptual evidence for using low doses of strong-agonistic insulin mimetopes for efficient human Foxp3+Treg induction and suppression of human autoimmunity." (PMID 26975663, 2016). "Alternatively, the TCR/FoxP3 gene-transduced iPSCs can be used to differentiate Ag-specific iPSC-Tregsin vivo and suppress autoimmune disorders." (PMID 26846186, 2016). "The expression of Foxp3 in B cells is critical for the immunoregulation of T cells and limits autoimmunity in a mouse model." (PMID 27350539, 2016). "Rorc and Foxp3 are key transcription factors for Th17 and Treg cells which have inverse impacts on autoimmunity." (PMID 25873156, 2015). "Application of regulatory T cells (Tregs) in transplantation, autoimmunity and allergy has been extensively explored, but how Foxp3 and Treg stability is regulated in vivo is incompletely understood." (PMID 25695215, 2015). "Th17 cells have an autoinflammatory potential and support the immune response against extracellular bacteria, whereas Foxp3-positive Tregs have a suppressive role and protect the organism from autoimmunity." (PMID 26635744, 2015). "Naturally occurring CD4+CD25+ regulatory T cells (nTreg) play an indispensable role in preventing autoimmunity mostly via Foxp3-dependent transcription." (PMID 25880134, 2015). "One of these effects is to increase FOXP3+ regulatory T cells (Treg), which play an immunosuppressive role in the body as a surveillance measure against development of autoimmunity." (PMID 25789179, 2015). "In an EAE mouse model of multiple sclerosis, IL-2 treatment resulted in restoration of FOXP3 expression, Treg stability, and prevention of autoimmunity." (PMID 26834735, 2015). "Although there is great interest in harnessing the immunosuppressive potential of FOXP3+ regulatory T cells (Tregs) for treating autoimmunity, a sizeable knowledge gap exists regarding Treg fate in human disease." (PMID 26561546, 2015). "Both Aire and FOXP3 are transcription factors essential to prevent autoimmunity and to maintain immunological homeostasis." (PMID 26457200, 2015). "The role of FoxP3+ve T-regs in autoimmunity and their intra-plasticity with Th17 cells is an area of active interest in a variety or autoimmune disorders." (PMID 25933188, 2015). "JHMV infection induces both Ag-specific and Foxp3+ regulatory T cells which are efficient at controlling autoimmunity in other settings." (PMID 26559484, 2015). "Regulatory T cells (Tregs), specifically CD4+CD25+ and Forkhead box P3+ (FoxP3+) Tregs, acquired notable attention because of their role in a variety of autoimmune pathologies." (PMID 26788051, 2015). "Inducible CD4+CD25+Foxp3+ regulatory T cells (iTreg) develop outside of the thymus and play an essential role in controlling of chronic inflammation and autoimmunity." (PMID 25393765, 2014). "Their unique capacity to prevent autoimmunity renders CD4+Foxp3+ Treg an attractive tool for the treatment and modulation of autoimmune diseases." (PMID 23446139, 2013).
Autoimmunity (continued). "On the other hand, the presence of Foxp3 (a marker for T regulatory cells) is believed to identify regulatory responses that when dominant, control autoimmunity." (PMID 23805032, 2013). "Naturally occurring CD4+CD25+Foxp3+ regulatory T cells play an essential role in regulating immune responses and preventing autoimmunity." (PMID 23755918, 2013). "Tregs constitute a heterogeneous population has been bolstered by the identification of a population of CD8+ Foxp3+ T cells in autoimmune disorders and after allergen exposure." (PMID 23437165, 2013). "In both mouse models, Foxp3+ Treg cell depletion by the in vivo administration of DT promotes the development of autoimmune disorders, albeit with differences in the severity of autoimmune symptoms." (PMID 23691523, 2013). "The mechanism underlying these effects involves not only CD4+ FoxP3− effector T cells (Teff cells) but also CD4+ FoxP3+ regulatory T cells (Treg cells), which prevent GVHD and autoimmunity, produced by the allotransplanted thymus." (PMID 23762092, 2013). "Tregs are recently known to express FoxP3 (forkhead box P3), an essential Transcription Factor for immune homeostasis and for prevention of autoimmunity." (PMID 23783557, 2013). "Deletion of another component of the miRNA machinery, drosha, specifically in Foxp3-expressing cells resulted in autoimmunity and overexpression of IFNγ and IL-4." (PMID 23345540, 2013). "Foxo1 and Foxo3a directly bind to Foxp3 promoter and increase the expression of Foxp3, and the deletion of Foxo results in the collapse of T-cell homeostasis and in the severe autoimmunity." (PMID 23383714, 2013). "Regulatory T cells are characterized by the expression of the transcription factor, Foxp3, and play a central role in preventing pathological immune responses including autoimmunity, allergy, and transplantation." (PMID 23894540, 2013). "In CVID, low proportions of CD4 + CD25+, Foxp3 T regulatory cell subset correlated with presence of autoimmunity and splenomegaly." (PMID 24044622, 2013). "Immune regulation by CD4+CD25+FoxP3+ regulatory T-cells (Tregs) and 17β-estradiol is crucial in the pathogenesis of sex bias in cancer and autoimmunity." (PMID 23577207, 2013). "The thymus is known to produce a regulatory CD4+ T-cell subset (Treg), fundamental for preventing autoimmunity, currently best identified by expression of the forkhead box P3 transcription factor (FoxP3)." (PMID 22590644, 2012). "Mice that have conditional deletion of Dicer in T reg cells showed early onset of autoimmunity which is similar to the observed phenotype in Foxp3 mutant mice that completely lack T reg cells." (PMID 22401860, 2012). "In contrast to Th17 cells, CD4+CD25+ and FOXP3+ (Tregs) play a critical role in maintaining self-tolerance and in preventing organ-specific autoimmunity, allergy, and allograft rejection." (PMID 23345934, 2012). "In the current study, CTLA4, FOXP3 and HLA were selected because T lymphocytes play a major role both in tumor immunity and autoimmunity and these genes are well known to directly or indirectly affect T cell function." (PMID 22911710, 2012). "CD4+ CD25+ forkhead box P3 (FoxP3)+ regulatory T cells (T reg cells) are known to suppress adaptive immune responses, key control tolerance and autoimmunity." (PMID 22373353, 2012). "Adaptive Tregs differentiated in vitro to express Foxp3 (iTregs) are gaining high interest as potential therapeutics for inflammatory conditions such as autoimmunity, allergy and transplant rejection." (PMID 22957107, 2012). "Suppressive Treg cells, expressing the forkhead transcription factor Foxp3, can lose the expression of Foxp3 and acquire the ability to produce pro-inflammatory cytokines during autoimmunity." (PMID 22720031, 2012). "Defects in the Foxp3 gene function in humans and mice result in fatal autoimmunity, and Foxp3 over-expression in previously naïve T cells converts them to Treg-like cells with in vivo and in vitro suppressive function." (PMID 22182475, 2011).